IL33 (interleukin 33)
Diseases named in the same sentence as IL33 in open-access papers (continued):
Sharing a sentence is not in itself a finding about the gene and the disease.
colon carcinoma (continued). "However, the exact role of IL33 is yet to be determined as the literature also provides studies that show an antiproliferative effect of this interleukin and an inhibition of colon cancer growth." (PMID 38398137, 2024). "In cancer patients, we observed a weaker correlation between IL8 and IL17A; however, there is a square correlation to be noticed between IL17A and IL33 (this study leaning to a direct response of circulating IL33 to IL17A variations in colon cancer development)." (PMID 38398137, 2024). "Previous studies demonstrated that IL-33 in colon cancer could activate core stem-cell genes and induce the phosphorylation of JNK activation and enhanced binding of c-Jun to the promoters of core stem-cell genes." (PMID 35382168, 2022). "Similarly, endogenous IL-33 promoted the expansion of IFN-γ+CD4+ T cells in tumor mouse models for colon carcinoma and hepatocellular carcinoma." (PMID 34209038, 2021). "In mouse models of colon carcinoma, endogenous IL-33 overcame the pro-tumorigenic effect of Treg by increasing IFN-γ production of tumor-infiltrating CD4+ and CD8+ T cells, as well as the accumulation of these infiltrating CD8+ T cells, exerting their anti-tumor effect." (PMID 34209038, 2021). "Furthermore, blocking IL-33 decreased mucositis and extended treatment of ectopic colon carcinoma with Irinotecan, resulting in a favorable outcome of the chemotherapy." (PMID 34209038, 2021). "Furthermore, several recent reports have supported an antitumorigenic role of the IL-33/ST2 axis in colon cancer." (PMID 34071419, 2021). "In addition, in mouse models of breast and colon cancer, IL-33 induced the recruitment of M2-like macrophages into the TME, contributing to tumor progression." (PMID 34209038, 2021). "IL-33 promotes tumor progression in mouse breast, lung and colon cancers and human colon cancer." (PMID 32340025, 2020). "IL-33 administration promotes stemness in colon cancer cells by recruiting macrophages." (PMID 33308251, 2020). "In conclusion, tumor IL-33 increase and stromal ST2 decrease are associated with greater desmoplasia in left colon tumors, which in turn might contribute to the development of lymphatic metastasis." (PMID 31281317, 2019). "Importantly, IL-33 blockade reduced mucositis and enabled prolonged irinotecan treatment of ectopic colon carcinoma leading to a beneficial outcome of the chemotherapy." (PMID 30483263, 2018). "Similarly, the expression of IL-33 by intestinal epithelial cells was increased in the murine azoxymethane/DSS model of colon cancer, and the authors went further to demonstrate that the epithelial expression of IL-33 was driven by epidermal growth factor." (PMID 29922293, 2018). "IL-33 inhibits colon cancer growth by suppressing cellular proliferation and promoting apoptosis." (PMID 30405626, 2018). "Similarly, in colon cancer cells, IL-33 stimulated cell sphere formation and prevented chemotherapy-induced tumor apoptosis." (PMID 30619376, 2018). "Moreover, using patient derived primary CRC cell lines as well as a mouse model of CRC, IL-33 was also suggested to activate colon tumor stroma and promote polyposis in vivo." (PMID 28715472, 2017). "We further characterized a TE-gene chimeric transcript involving the Interleukin 33 (IL-33) gene (termed LTR-IL-33), that is ectopically expressed in a subset of colon cancer samples through the use of an endogenous retroviral long terminal repeat (LTR) promoter of the MSTD family." (PMID 28715472, 2017). "The purpose of this study was to evaluate IL8, IL17, and IL33 concentrations in healthy and colon cancer patients and their variation in different stages of this malignancy and to establish the existence of any correlations between these three interleukins in colon cancer progression." (PMID 38398137, 2024). "Finally, we also tested whether the effects of colon cancer cell supernatant and IL-33 were additive." (PMID 32923137, 2020).
colon carcinoma (continued). "Moreover, the correlation between decreased IFN-γ secretion and colon cancer aggressiveness, suggests that IL-33 signaling defects may impair the generation of IFN-γ-mediated immunity." (PMID 30416507, 2018). "The study of colon cancer has been significantly enriched by the understanding of the roles of specific interleukins, particularly IL8, IL17A, and IL33." (PMID 38398137, 2024). "For example, exogenous IL33 stimulation or IL33 overexpression in tumor cells confers stemness on tumor cells through ST2 signaling to activate NANOG, NOTCH, and OCT3/4 in colon cancer and hepatocellular carcinoma." (PMID 33535613, 2021). "M2-like TAMs stimulated by IL-33 produced prostaglandin E2 (PGE2) and thereby facilitated colon cancer stemness and tumor growth." (PMID 34209038, 2021). "Our previous research clarified that IL-33 binds to its receptor ST2 and induces phosphorylation of c-Jun N-terminal kinase activation (JNK), which leads to the expansion of colon cancer cell stemness." (PMID 33062675, 2020). "IL-33 in the TME recruits macrophages and stimulates their production of PGE2, and in turn, macrophage-derived PGE2 stimulates colon tumor development." (PMID 30416507, 2018). "Considering the link between IL-33 and M2-like macrophages in other reports 28 and our clinical samples, we examined the intratumoral infiltration of M2-like macrophages in a CT26 colon cancer model that had an immunocompetent TME." (PMID 37056569, 2023). "Herein, using a murine model of intestinal-type colon cancer we report the presence of high levels of SCF and IL-33 in the TME which coincides with the accumulation of TAMCs with a connective-like phenotype that through the production of TNF-α and IL-6 contributes to a pro-inflammatory environment." (PMID 37730723, 2023). "Similarly, IL-33 was reported to amplify IFN-γ+ CD4+ T cells in mouse models of hepatocellular and colon carcinoma." (PMID 33329534, 2020). "The IL-33/ST2 pathway upregulates CD40L and suppresses the growth of murine colon cancer." (PMID 33308251, 2020). "IL33 (interleukin 33) induces the phosphorylation of c-Jun N terminal kinase (JNK), recruits macrophages into the cancer microenvironment, and promotes the carcinogenesis of colon cancer." (PMID 33628738, 2020). "The recruitment of macrophages in the TME might account for the stimulation of CCL2 expression by IL-33-stimulated cancer cells that express ST2, such as human colon cancer cells." (PMID 30416507, 2018).
lung carcinoma (54 papers, 2016 to 2026). "Recent studies have linked IL-33 to various cancers, including lung cancer, liver cancer, head and neck squamous cell carcinoma." (PMID 41333471, 2025). "IL-33 and IL-13 have been implicated in the progression of other cancers, such as breast and lung cancers." (PMID 40761291, 2025). "According to several recent studies, interleukin-33 has been linked to the advancement of lung cancer and can have opposing effects on the disease depending on the circumstances." (PMID 36874133, 2023). "IL-33 has been reported to be strongly associated with lung cancer progression, and can exhibit opposite effects on lung cancer under different conditions." (PMID 35634336, 2022). "Once the C allele at the rs4742170 site in lung cancer cells mutated to become a T allele, it was observed that the GR binding site was destroyed and the binding force between the GR and the IL33 gene was reduced." (PMID 34977013, 2021). "Although it has been suggested that IL-33 is implicated in tumor-associated immune responses and inflammatory diseases of the lung, its role in lung cancer progression is still being debated." (PMID 31130612, 2019). "Firstly, they demonstrated the role of type 2 innate lymphoid cells (ILC2) in individuating and eliminating lung cancer cells, showing that neoplastic elements grew more rapidly and had a higher frequency of metastasis in IL-33 and/or ILC2-deficient mice." (PMID 31130612, 2019). "IL-33 expression was inversely correlated with progressive stages of human lung cancers and lower levels were associated with poor prognosis of pulmonary carcinoma." (PMID 30205617, 2018). "Analysis of five independent TCGA and GEO lung cancer expression datasets further revealed that higher expression levels of IL-33 mRNA were associated with longer overall survival of adenocarcinoma patients." (PMID 29499051, 2018). "The observed decreases indicate that the expression levels of IL-33 are inversely associated with lung cancer progression." (PMID 30483263, 2018). "Furthermore, the Th2 inflammatory cytokine IL-33 is associated with poor prognosis in lung cancer patients." (PMID 32714316, 2020). "In contrast, similar patient-based studies suggested that serum IL-33 may be a useful diagnostic biomarker in lung cancer." (PMID 30205617, 2018). "It should be pointed out that plasma IL-33 levels could be inversely associated with progression of lung cancer." (PMID 29568370, 2018). "An anti-tumorigenic role for IL-33 in lung cancer was proposed in studies showing that male patients who had a history of smoking had significantly lower plasma IL-33 levels as compared to healthy controls and that IL-33 expression was inversely associated with progression of lung cancer." (PMID 30205617, 2018). "In addition, the association between expression levels of IL-33 mRNA and patient survival was determined using 5 independent expression profiling datasets of human lung cancer." (PMID 29499051, 2018). "In this paper, we demonstrate that the presence of rs928413(G) allele in the IL33 promoter indeed results in its increased activity in a human lung carcinoma cell line due to binding of the cAMP (cyclic adenosine monophosphate) response element binding protein 1 (CREB1) transcription factor." (PMID 30257479, 2018). "Recent studies have indicated that lung cancer cells can release IL-33, promote M2 macrophage polarization, and enhance tumor cell immune escape." (PMID 40216748, 2025). "In this study, we investigated the specific role of IL-33 from both CAFs and tumor cells in regulating the chemosensitivity of lung cancer." (PMID 40216748, 2025). "Taken together, these data indicate that IL-33 expression in lung cancer cells is negatively correlated with the efficacy of DNA damage-inducing chemotherapeutic drugs." (PMID 40216748, 2025).
lung carcinoma (continued). "To explore the potential role of ST2+ macrophages in lung cancer, we analyzed the correlation between IL-33 and ST2 mRNA levels and macrophage infiltration in lung adenocarcinoma (LUAD) and lung squamous cell carcinoma (LUSC) using TCGA datasets." (PMID 38778059, 2024). "Here, we identify the cisplatin-induced danger signal IL-33, which promotes M2 macrophages to reduce the anti-tumor effect of cisplatin in lung cancer." (PMID 38778059, 2024). "In preclinical trials, blocking IL-33 signalling with an anti-IL-33 or anti-ST2 antibody showed efficacy in patients with lung cancer." (PMID 38662248, 2024). "This is the first time that IL25-activated ILC2 cells’ role in lung cancer has been studied and our results indicate that such cells bear tumor-promoting functions, in contrast to IL-33-activated ILC2 cells." (PMID 37781372, 2023). "Interleukin-33 enhances the programmed oncosis of ST2L-positive low-metastatic cells in the tumor microenvironment of lung cancer." (PMID 37569328, 2023). "Similar with the bioinformatics results in TCGA database, our experiments confirmed the expression of CLEC7A, TLR7, IL-1A and IL33 were decreased in lung cancer." (PMID 37259066, 2023). "According to the existing research results, we believe that there is a possibility of clinically using IL-33 to specifically enhance the function of immune cells in the treatment of lung cancer." (PMID 35634336, 2022). "A study selected 125 NSCLC patients and found that patients with relatively higher expression of IL-33 in the paracancerous tissue were more likely to develop the poorly differentiated lung cancer and lymph node metastasis." (PMID 35634336, 2022). "Serum level of IL-33 in lung cancer patients was reported similar, higher or lower compared with that in healthy volunteers in different studies, reflecting that the role of IL-33 in lung cancer is complex." (PMID 35634336, 2022). "IL-33 can play a dual role and has been reported to promote lung cancer in some studies and suppress lung cancer in others." (PMID 35634336, 2022). "A number of previous studies have indicated that IL-33 exerts anti-lung cancer effects under certain conditions, while driving lung cancer progression in other circumstances." (PMID 35634336, 2022). "In summary, if the IL-33-TGF-β niche signaling loop is also present in lung cancer, it will be necessary to investigate that why IL-33 levels were relatively lower in lung cancer tumor tissues." (PMID 35634336, 2022). "We have highlighted the dual regulation of IL-33 in lung cancer and proposed potential lung cancer treatment regimens, especially new immunotherapies, based on its mechanism of action." (PMID 35634336, 2022). "Five of the seven genes (BIRC5, GIMAP5, HBB, IL33, and AKAP12) associated with the LC-LK alignments have been observed to be deregulated in lung cancer." (PMID 36101460, 2022). "According to the existing results, we assume that the level of Tregs in the tumor tissue is an important determinant of IL-33 function in lung cancer." (PMID 35634336, 2022). "Programed oncosis of ST2L-positive low-metastatic cells induced by interleukin-33 in tumor microenvironment of lung cancer led to a slower tumor growth." (PMID 34389740, 2021). "In an in vitro study, IL-33 was able to directly induce migration and invasion of the A549 lung cancer cells." (PMID 34209038, 2021). "By comparing the proportion and function of ILC2s infiltrating two different types of lung cancer (a primary tumor producing high IL-33 and a metastatic tumor producing low IL-33), ILC2s were reduced in metastatic- in comparison to primary tumor." (PMID 33233582, 2020). "Consistent with previous evidence, interleukin-33 (IL33) and interleukin 1 receptor-like 1 (IL1RL1) were found to be increased in lung cancer and associated with disease clinical stage." (PMID 33005178, 2020).
lung carcinoma (continued). "IL-33 was seen to augment the cell death of ST2L-positive low-metastatic cells, but not of the ST2L-negative high-metastatic cells, suggesting that IL-33 enhances lung cancer progression by selecting for more malignant cells in the tumor microenvironment." (PMID 31231372, 2019). "According to these data, the bronchial epithelium and the vascular endothelium were suggested to be the source of the elevated IL-33 serum levels during the early stages of lung cancer." (PMID 31130612, 2019). "Levels of IL-33 have also been shown to negatively correlate with tumor stage in multiple myeloma patients and lung cancer patients." (PMID 31231372, 2019). "They determined the reduction of Treg cells in experimental lung cancer after administering anti-IL-33 and anti-ST2." (PMID 31130612, 2019). "Since IL-33 has been shown to be involved in various lung diseases, we set out to study IL-33 expression during human lung cancer development." (PMID 29499051, 2018). "We demonstrated that risk “G” rs928413 allele creates a CREB1 binding site that is sufficiently strong to provide a significant boost in IL33 transcriptional activation in lung carcinoma cells." (PMID 30544846, 2018). "Nevertheless, the exact role of IL-33 in lung cancer development needs to be established using appropriate mouse models of lung cancer." (PMID 29499051, 2018). "Activation of epithelial and endothelial cells during the early stages of lung cancer was thought to trigger the release of IL-33." (PMID 30205617, 2018). "We first sought to examine the expression pattern of IL-33 in adjacent normal lung tissues from lung cancer patients." (PMID 29499051, 2018). "IL-33 expression in lung cancer cells reduces tumor growth in vivo, restores MHC-I expression and immunovisibility." (PMID 30483263, 2018). "We propose tumoral IL-33 expression and its function in tumor progression as an individualized element to be considered in lung cancer patients." (PMID 29568370, 2018). "These constructs were tested in a NCIH-196 human lung carcinoma cell line, which is characterized by constitutive IL33 expression, according to Broad-Novartis Cancer Cell Line Encyclopedia." (PMID 30257479, 2018). "Herein, we determined the pro-cancer activity of IL-33 in tumor progression using fresh isolated cancer cells from lung cancer patients." (PMID 28978138, 2017). "To understand the role of the IL-33/ST2L axis in lung cancers, we sought to identify lung cancer cells expressing functional ST2L." (PMID 26775708, 2016). "The increased frequency and number of innate and adaptive immune cells in IL-33 - expressing tumours supports the conclusion that tumour-infiltrating immune cells mediate protective anti-tumour immunity in murine lung carcinoma." (PMID 27619158, 2016). "A11 tumour tissues contained a very low level of IL-33, which is in accordance with the observation that more malignant human lung cancers express lower levels of IL-33." (PMID 26775708, 2016). "Experiments have suggested that antibodies blocking IL-1β can prevent cardiovascular events and reduce the incidence and mortality of lung cancer, emphasizing the importance of IL-1 and related family members (such as IL-33 and IL-18) in shaping the innate immunity and inflammation responses." (PMID 41333471, 2025). "First, we found that CAFs isolated from lung cancer patients expressed high levels of IL-33, which could dramatically promote chemoresistance of cancer cells upon co-culturing." (PMID 40216748, 2025). "Moreover, we demonstrated that cisplatin-treated lung cancer cells significantly increase IL-33 release, promoting M2 macrophage polarization and enhancing tumor cell immune escape." (PMID 38778059, 2024). "They concluded that enhancing IL-33/ST2 signaling was able to markedly promote the malignant growth of lung cancer cells, while down-regulating or blocking IL-33/ST2 signaling could inhibit this process." (PMID 35634336, 2022).